RNU6-456P (RNA, U6 small nuclear 456, pseudogene)
Gene: Small nuclear RNA gene on chromosome 5 (134,500,178 to 134,500,284, reverse strand). Ensembl gene ENSG00000207222.
Homologues: Orthologues: chimpanzee U6 (100% identical), macaque U6 (93% identical), guinea pig U6 (88% identical), mouse Gm22808 (83% identical), dog U6 (78% identical), rat U6 (78% identical), pig U6 (75% identical). Paralogues in human: RNU6-1011P (93% identical), RNU6-1060P (90% identical), RNU6-15P (90% identical), RNU6-12P (89% identical), RNU6-13P (89% identical), RNU6-166P (89% identical), RNU6-26P (89% identical), RNU6-31P (89% identical), RNU6-32P (89% identical), RNU6-33P (89% identical), RNU6-38P (89% identical), RNU6-41P (89% identical), and 1285 more.